OR7A2P (olfactory receptor family 7 subfamily A member 2 pseudogene)
Description:
Odorant receptor.
Synonyms: hg1003; OR19-18; OLF4p; formerly OR7A7; OR7A2
Gene: Transcribed unprocessed pseudogene on chromosome 19 (14,863,786 to 14,864,715, reverse strand). Ensembl gene ENSG00000172148.
Subcellular location: Cell membrane